OR5L1 (olfactory receptor family 5 subfamily L member 1)
Description:
Odorant receptor.
Synonyms: OST262; OR11-151
Tractability: Antibody: UniProt places it where antibodies can reach, with medium confidence; UniProt predicts a signal peptide or a membrane-spanning region; its Gene Ontology location is reachable by antibodies, with medium confidence.
Gene: Protein-coding gene on chromosome 11 (55,811,367 to 55,812,476, forward strand). Ensembl gene ENSG00000279395.
Subcellular location: Cell membrane
Pathways (Reactome):
Sensory Perception: Expression and translocation of olfactory receptors
Gene Ontology:
Molecular function: olfactory receptor activity; G protein-coupled receptor activity
Biological process: G protein-coupled receptor signaling pathway; sensory perception of smell; detection of chemical stimulus involved in sensory perception of smell
Cellular component: plasma membrane; membrane
Genetic constraint (gnomAD): Loss-of-function variants: 0 observed, 0.0749 expected, observed/expected ratio (o/e) 0, 90% interval 0 to 1.89. That is too few expected variants to judge how well the gene tolerates losing a copy. Missense variants: 398 observed, 371.23 expected, observed/expected ratio (o/e) 1.07, 90% interval 0.99 to 1.16. Synonymous variants: 197 observed, 148.33 expected, observed/expected ratio (o/e) 1.33, 90% interval 1.18 to 1.5.
Homologues: Orthologues: chimpanzee OR5L1 (99% identical), macaque OR5L1 (91% identical), dog OR5L1 (83% identical), dog OR5L1C (82% identical), dog OR5L1B (80% identical), mouse Or5l14 (80% identical), rat Or5l14b (75% identical), rat Or5l13 (75% identical), mouse Or5l13 (74% identical). Paralogues in human: OR5L2 (92% identical), OR5D18 (62% identical), OR5D16 (58% identical), OR5D14 (57% identical), OR5D3 (54% identical), OR5AP2 (53% identical), OR5I1 (53% identical), OR5B12 (53% identical), OR5W2 (53% identical), OR9I1 (52% identical), OR5B21 (52% identical), OR5D13 (52% identical), and 84 more.
Diseases named in the same sentence as OR5L1 in open-access papers:
OR5L1 is named in the same sentence as 1 disease in open-access papers, as found by Europe PMC text mining. Sharing a sentence is not in itself a finding about the gene and the disease. The quoted sentences say what the papers report.
fibroepithelial polyp (1 paper, 2025). A polypoid lesion composed of fibrous tissue and epithelium. "The other mutations found in our case (DNMT3A, C8B, TET2, SDHA, ARID1B, NOTCH1, OR5L1, and KDM6A) do not have a known association with the formation of fibroepithelial polyps." (PMID 40936011, 2025).